DHX15 (DEAH-box helicase 15)
Diseases named in the same sentence as DHX15 in open-access papers (continued):
Sharing a sentence is not in itself a finding about the gene and the disease.
acute promyelocytic leukemia (1 paper, 2017). An aggressive form of acute myeloid leukemia (AML), characterized by arrest of leukocyte differentiation at the promyelocyte stage, due to a specific chromosomal translocation t(15;17) in myeloid cells. "The distinctive expression pattern of DHX15 suggested its role in the regulation of myeloid differentiation; we, therefore, detected the expression level of DHX15 during differentiation induced by all-trans-retinoic acid (ATRA) in human acute promyelocytic leukemia cells (NB4 cells)." (PMID 29163777, 2017).
bladder cancer (1 paper, 2025). "Collectively, these results demonstrate that HDAC2-mediated delactylation at the K17 site of DHX15 promotes bladder cancer progression, at least in part, by modulating the alternative splicing and downregulating the mature RPL9 transcript." (PMID 41408324, 2025).
Burkitt lymphoma (1 paper, 2022). A rare form of malignant mature B-cell non-Hodgkin lymphoma. "DHX15 was overexpressed in Burkitt lymphoma patients and tends to be associated with poor progression-free survival and poor overall survival." (PMID 35193582, 2022). "However, the role of DHX15 in Burkitt lymphoma (BL) and latent Epstein-Barr virus (EBV) infection remains to be elucidated." (PMID 35193582, 2022). "DHX15 was overexpressed in patients with Burkitt lymphoma and downregulation of DHX15 gene promoted BL cells apoptosis, inhibited cell proliferation and BL tumor growth in vivo, suggesting that DHX15 might be a novel therapeutic target for the treatment of Burkitt lymphoma." (PMID 35193582, 2022).
cervical cancer (1 paper, 2022). A primary or metastatic malignant neoplasm involving the cervix. "In addition, we examined the mRNA expression of RNF4, OCIAD1, TMED5, DHX15, MED28, and LETM1 in TMEM33 knockdown cervical cancer cells." (PMID 35832191, 2022).
chronic obstructive pulmonary disease (1 paper, 2021). A chronic and progressive lung disorder characterized by the loss of elasticity of the bronchial tree and the air sacs, destruction of the air sacs wall, thickening of the bronchial wall, and mucous accumulation in the bronchial tree. "DHX15 is an ATP-dependent RNA helicase that has been shown to influence the risk of emphysema in chronic obstructive pulmonary diseases." (PMID 34336829, 2021).
Cirrhosis (1 paper, 2024). A chronic disorder of the liver in which liver tissue becomes scarred and is partially replaced by regenerative nodules and fibrotic tissue resulting in loss of liver function. "However, we did not detect significant differences in the Dhx15 circulating levels when we compared the HCC and the cirrhosis groups, despite detecting a trend of greater concentration of Dhx15 in patients with HCC." (PMID 38612527, 2024).
dengue (1 paper, 2022). "Amongst these, the three DEAD-box RNA helicases AAEL004419/Dhx15, AAEL008728, and AAEL004859 also acted as antiviral factors in dengue and CHIKV infections." (PMID 36441781, 2022).
latent infection (1 paper, 2022). "For example, we did not determine whether DHX15 could also promote the expression of EBV latent infection products in other EBV-associated tumors or whether DHX15 can be used as a target for treatment of latent EBV infection." (PMID 35193582, 2022). "It remains poorly understood whether DHX15 affects the expression of EBV latent infection products (EBNA-1, EBER-1, EBER-2) or participates in the development of BL." (PMID 35193582, 2022). "Furthermore, knockdown of DHX15 reduced EBV latent infection products expression and inhibited RNA polymerase III activity." (PMID 35193582, 2022). "Our results demonstrated that DHX15 could promoted tumor growth and upregulated EBV latent infection products." (PMID 35193582, 2022).
liver cancer (1 paper, 2020). An epithelial or non-epithelial malignant neoplasm that arises from the liver. "Overall, this study has identified a non-classic function of the RNA helicase DHX15 as a suppressor of autophagy and liver cancer, and the findings suggest that DHX15 may be a potential therapeutic element for liver cancer and autophagy-related diseases." (PMID 33644083, 2020). "We also detected the expression of DHX15 in human liver tissues which suggested DHX15 may be a vital factor in liver cancer." (PMID 33644083, 2020). "In addition, although we have revealed the role of DHX15 in some human liver cancer tissues, an examination of more samples is required to fully demonstrate its role, and the clinic outcome of liver cancer patients should be examined." (PMID 33644083, 2020). "In addition, we also detect the expression of DHX15 in human liver cancer tissues." (PMID 33644083, 2020). "In contrast, DHX15 may be a new clinical indicator of liver cancer progression and outcome." (PMID 33644083, 2020). "Moreover, identification of the precise target by which DHX15 regulates autophagy, which may contribute to further exploration of the role of DHX15 in liver cancer, remains to be identified." (PMID 33644083, 2020). "In conclusion, our study demonstrates a non-classical function of DHX15 as a negative regulator of autophagy related to the mTORC1 pathway and reveals that DHX15-related autophagy dysfunction promotes HCC cell proliferation, indicating that DHX15 may be a target for liver cancer treatment." (PMID 33644083, 2020).
liver disease (1 paper, 2024). "Therefore, our results support the potential role of DHX15 as a diagnostic and therapeutic target in liver disease, as well as a major regulator of liver regeneration and organogenesis." (PMID 38612527, 2024). "With this purpose, we performed serological evaluation of DHX15 levels by ELISA in a cohort of patients with different liver disease etiologies." (PMID 38612527, 2024). "Regarding the potential use of DHX15 as a diagnostic marker for liver disease, HCC patients showed increased levels of DHX15 in blood samples compared with subjects without hepatic affectation." (PMID 38612527, 2024).
lymphoma (1 paper, 2019). A malignant (clonal) proliferation of B- lymphocytes or T- lymphocytes which involves the lymph nodes, bone marrow and/or extranodal sites. "A similar correlation expression pattern for DHX15 was observed for the human lymphoma dataset as well as for a smaller lymphocyte dataset from healthy donors." (PMID 31921164, 2019).
prostate tumor (1 paper, 2019). "DHX15 is involved in the regulation of tumor cell growth and is thereby identified as a coactivator of prostate tumor progression." (PMID 31766457, 2019).
tumor (20 papers, 2017 to 2026). "We believe the presence of the other Dhx15 allele in heterozygous mice prevents us from seeing a net effect on the decrease in the primary tumor volume." (PMID 38612527, 2024). "Together, these data reveal that DHX15 is a receptor of F. nucleatum in tumor cells and is upregulated upon the p.G12D mutation." (PMID 38402201, 2024). "Considering the role played by lymphatic vessels in tumor invasion, we suggest, as a model, that the impaired lymphatic growth within the primary tumor associated with Dhx15 deficiency limited cancer cell invasion into other organs, including the liver." (PMID 38612527, 2024). "We found that heterozygous DHX15 deficiency partially inhibits primary tumor growth and reduced lung metastases." (PMID 34654883, 2021). "Collectively, these results show that DHX15 inhibits autophagy by activating mTORC1, which is associated with the anti-tumor effect of DHX15." (PMID 33644083, 2020). "Also, Dhx15 deficiency led to reduced hepatic tumor invasion and tumor growth in a murine HCC model." (PMID 38612527, 2024). "Moreover, loss of DHX15 has been found to inhibit energy metabolism in endothelial cells, and DHX15+/- mice presented partially inhibited tumor growth and reduced lung metastasis after injection of tumor cells." (PMID 40541951, 2025). "Here we show that the elevated expression of DHX15 is pertinent to KRAS p.G12D mutation and DHX15 as a specific receptor in the nuclei of tumor cells interact with F. nucleatum to mediated-colorectal tumorigenesis." (PMID 38402201, 2024). "Also, liver-specific targeting of Dhx15 silencing and the generation of a conditional knockout to restrict the Dhx15 deficiency to the liver are needed to ensure the safety of an anti-Dhx15 therapeutic strategy in the context of tumor treatment and to prevent side effects in other organs." (PMID 38612527, 2024). "Due to the effect of Dhx15 on tumor growth in our experimental model of HCC, we wanted to evaluate the differential diagnostic utility of this marker in patients." (PMID 38612527, 2024). "In accordance with reduced tumor nodule formation, we observed clear differences in WT and heterozygous mice, depicting vascular abnormalities in Dhx15+/− mice." (PMID 38612527, 2024). "We evaluated tumor invasion of the liver by Hepa 1-6 and found small nodules within the livers of Dhx15+/− mice compared to WT mice (65.62 ± 11.77 vs. 111 ± 15.92 μm of nodule size per mouse, respectively; p < 0.05)." (PMID 38612527, 2024). "Then, we established the HCC Hepa 1-6 model in AUMsilence ASO-injected mouse to target Dhx15 expression and we observed a significant reduction in average tumor growth." (PMID 38612527, 2024). "To analyze the level of DHX15 in patient samples, we performed IHC on tumor tissues of patients with CRC that harbor KRAS p.G12D, p.G13D mutations, and KRAS WT allele." (PMID 38402201, 2024). "Upon subcutaneous injection of Hepa 1-6 cells in the flank of WT and Dhx15+/− mice, we followed primary tumor formation." (PMID 38612527, 2024). "Here the authors show that F. nucleatum is enriched preferentially in patients with KRAS p.G12D mutant CRC and that it promotes colorectal tumorigenesis in preclinical models by binding DHX15 on tumor cells." (PMID 38402201, 2024). "To further study the effects of DHX15 gene knockdown on the tumorigenic phenotype of BL and its contribution to tumor growth in vivo, we successfully established a xenograft model of human BL." (PMID 35193582, 2022). "In vivo study, HE, IHC, TUNEL and ISH assays were used to analyze the effect of DHX15 on subcutaneous tumor nodes formation." (PMID 35193582, 2022). "Considering also that one of the pathways modified by the reduction of DHX15 was “endocrine system disorders, organismal injury and abnormalities and cancer”, we aimed at evaluating the role of DHX15 in tumor development." (PMID 34654883, 2021).
tumor (continued). "The results of our study revealed a vascular regulatory role for DHX15 that has an impact in pathological processes such as impaired lymphatic drainage and tumor growth." (PMID 34654883, 2021). "In all these situations, modifications of DHX15 activity and/or its overexpression favors tumor growth." (PMID 34654883, 2021). "In our study, we provided an additional mechanism of DHX15 that is relevant for tumor progression: the regulation of vascular growth and function." (PMID 34654883, 2021). "After injection of syngeneic LLC1 tumor cells, DHX15+/− mice showed partially inhibited primary tumor growth and reduced lung metastasis." (PMID 34654883, 2021). "The data showed that the levels of DHX15 (mainly distributed in the cytoplasm) were higher in adjacent normal tissues than in tumor tissues (15 of the 20 sample pairs)." (PMID 33644083, 2020). "Clinical validation of potential tumor markers such as DHX15 will clearly continue to be a major focus of GC research in the next few years." (PMID 28493890, 2017). "Knocking out Dhx15 in mice with KRAS p.G12D mutant CRC reduces tumor progression." (PMID 40231893, 2025). "Furthermore, the tumor-suppressive role of circRNF10 on BC proliferation was partially abolished by knocking down of DHX15." (PMID 37101128, 2023). "Additionally, IHC results showed that overexpression of circRNF10 reduced Ki-67, p65, and DHX15 levels in BC tumor, which were consistent with the role circRNF10 played in vitro in BC." (PMID 37101128, 2023). "Compared with overexpressing DHX15 alone, circRNF10 could partially eliminate the tumor-promoting effects induced by elevated DHX15 expression." (PMID 37101128, 2023). "In summary, silencing DHX15 gene could promote BL cells apoptosis, inhibit cell proliferation in vitro and BL tumor growth in vivo, indicating that DHX15 might be a novel therapeutic target of the treatment for BL." (PMID 35193582, 2022). "Moreover, we found that DHX15 gene knockdown inhibited tumor growth and downregulated EBNA-1, EBER-1, EBER-2 in vivo." (PMID 35193582, 2022). "Recently, DHX15 has been reported to be a tumor-related factor." (PMID 33644083, 2020). "F. nucleatum binds to the DHX15 protein on CRC cells, activating the ERK/STAT3 signaling pathway, which promotes tumor growth." (PMID 40231893, 2025). "F. nucleatum invades intestinal epithelial cells and binds to DHX15, a protein of RNA helicase family expressed on CRC tumor cells, mechanistically involving ERK/STAT3 signaling." (PMID 38402201, 2024). "Recent studies have reported that RNA helicases play a role in the progression of a variety of tumor types, including DHX9, DHX15, DDX24, DHX29, and DHX36." (PMID 37958405, 2023). "Five weeks after injection, Dhx15+/− mice exhibited similar tumor size and low, nonsignificant expression levels of the HCC marker alpha-fetoprotein (AFP) compared to wild-type mice." (PMID 38612527, 2024). "Therefore, the absence of Dhx15, either in heterozygosis or due to specific Dhx15 silencing, translates into an antitumor effect when analyzing tumor invasion or the size of the primary tumor." (PMID 38612527, 2024). "Furthermore, we evaluate the functions of Dhx15 in HCC and liver metastasis, in Dhx15 heterozygous mice and using the self-delivering AUMsilence ASO technology, providing evidence for its role in the regulation of metastasis and primary tumor growth." (PMID 38612527, 2024).
cancer (16 papers, 2016 to 2025). A tumor composed of atypical neoplastic, often pleomorphic cells that invade other tissues. "DHX15 has also been implicated in cancer, through its role in splicing and because it binds proteins like c-MYC." (PMID 40168451, 2025). "Mutations in splicing factors typically occur in many cancers; therefore, recent DHX15 studies have focused on elucidating its role in different types of cancer." (PMID 38612527, 2024). "Studies also suggest that DHX15 contributes to carcinogenesis in some cancer types or acts as a tumor suppressor gene in others." (PMID 40168451, 2025). "As a core component of the spliceosome, DHX15 is critical for pre-mRNA processing, yet its role, particularly in the context of cancer and post-translational regulation, remains incompletely understood." (PMID 41408324, 2025). "Further studies analyzing the specificity of DHX15 in cancer and metastasis are necessary, especially as oncologic complications are highly related to metastasis appearance." (PMID 38612527, 2024). "To start evaluating the potential therapeutic benefits of Dhx15 inhibition in cancer and metastasis, we designed specific Dhx15-inhibiting oligonucleotides for in vivo use." (PMID 38612527, 2024). "They further elucidate the effect of cancer-associated mutations in SF3B1 and SUGP1 that weaken their interaction, disrupting the formation of a larger complex with DHX15 and causing pre-mRNA splicing defects." (PMID 37977822, 2023). "In LIHC, DHX9, DHX32, and DHX15 play important roles in promoting cancer cell motility and proliferation, inhibiting cell apoptosis, and indicating a poor prognosis." (PMID 35814441, 2022). "Although both autophagy and DHX15 are involved in cellular metabolism and cancer progression, their exact relationship and mechanism remain elusive." (PMID 33644083, 2020). "Recently, several studies have analyzed the role of DHX15 in different cancer types." (PMID 38612527, 2024). "Most current research on DHX15 is focused on cancer and immunity." (PMID 38699234, 2024). "Recent studies evaluate the role of DHX15 in different cancer types." (PMID 38612527, 2024). "The loss of interaction between SF3B1 and SUGP1 due to cancer mutations in either SF3B1 or SUGP1 provides an explanation for why the mutant spliceosome fails to activate DHX15 for ATP hydrolysis required for canonical branch site selection." (PMID 37977822, 2023). "Studies have reported that overexpression of DHX15 is related to cancer progression." (PMID 35193582, 2022). "Moreover, the TMEM33 expression level was remarkably positively correlated with similar genes of RNF4, OCIAD1, TMED5, DHX15, MED28 and LETM1, which have been reported to be implicated in tumorigenesis of various cancers." (PMID 35832191, 2022). "DHX15 play key role in cancer progression through activating AR activity through Siah2-mediated ubiquitination independent of its ATPase activity, but this gene might be liable for development of pituitary prolactinoma." (PMID 33709028, 2021). "Therefore, DHX15 is a versatile protein that participates in different stages of many types of cancers." (PMID 33644083, 2020). "And the mechanism between DHX15 and autophagy maybe the potential prognostic indicator in cancer therapy." (PMID 33644083, 2020). "DHX15, as an RNA helicase, is required for SUGP1 and participates in RNA error mediated by SF1B3 in cancer." (PMID 38699234, 2024). "Following previous observations by us and others regarding the function of DHX15 in HCC, we decided to evaluate the potential therapeutic use of Dhx15 deletion in the cancer setting." (PMID 38612527, 2024). "Finally, we showed that the relative proportion of sites with increased vs. decreased editing levels could be partially explained by the differential expression of three RNA binding proteins – RPS14, SRSF9 and DHX15 – in a subset of the cancer types we analyzed (Supplementary Results)." (PMID 26980570, 2016).
cancer (continued). "Overexpression of DHX15, EIF4A3, and RBM17 splicing factors have been demonstrated in cancer." (PMID 34944912, 2021). "Additionally, unlike both SUGP1 and DHX15, DDX46 is not known to harbor any cancer-associated mutations that recapitulate mutant SF3B1 missplicing." (PMID 37977822, 2023).
infection (7 papers, 2014 to 2024). The state of being infected such as from the introduction of a foreign agent such as serum, vaccine, antigenic substance or organism. "In Drosophila cells, DHX15 was identified as an activator of JNK, P38, and NF-kB pathways in response to polyI:C and infection with an RNA virus to mediate cytokine production and apoptosis." (PMID 39772220, 2024). "Notably, SOD1 is an important interaction molecule that exists both in BALF, PBMC and serum, and participates in early and late stages of infection, followed by PRKAR1A, IARS, SNRNP200, and DHX15." (PMID 34952961, 2021). "In human cells, Dhx15 activates MAPK and NFκB signaling during antiviral responses triggered by poly I:C as well as during infection with positive and negative sense RNA viruses." (PMID 36441781, 2022).
DHX15 also shares sentences with these, for which no sentence is quoted: acute lymphoblastic leukaemia (2 papers); glioblastoma (2); asthma (1); cardiac hypertrophy (1); chronic hepatitis B (1); chronic neutrophilic leukemia (1); colorectal cancer (1); emphysema (1); endocrine system disorder (1); endometrial carcinoma (1); gastrointestinal disease (1); heart failure (1); lung adenocarcinoma (1); lymphopenia (1); multiple myeloma (1); myelodysplastic syndrome (1); non-small cell lung carcinoma (1); psoriasis (1); renal carcinoma (1); reovirus infection (1); severe congenital neutropenia (1); small cell lung carcinoma (1).